MTOR (mechanistic target of rapamycin kinase)
Diseases named in the same sentence as MTOR in open-access papers (continued):
Sharing a sentence is not in itself a finding about the gene and the disease.
renal carcinoma (continued). "In renal cancer, constraints in activation of the PI3K/mTOR pathway, which manifests as the shared pathway of mutations in PTEN, PIK3CA, TSC1, or mTOR, might be exploitable for therapeutic benefit." (PMID 29764517, 2018). "Here, we summarize potential targeting strategies for renal cancer cells and renal CSCs, including tyrosine kinase inhibitors, mammalian target of rapamycin inhibitors (mTOR), interleukins, CSC marker inhibitors, bone morphogenetic protein-2, antibody drug conjugates, and nanomedicine." (PMID 27891093, 2016). "Indeed, it remains to be seen if novel combination therapies using mTOR inhibitors can target both renal cancer cells and renal CSCs." (PMID 27891093, 2016). "As the CXCR4–CXCL12–CXCR7 axis and the mTOR pathway were described to regulate cell growth in renal cancer, we wished to evaluate whether targeting the two pathways might affect cell proliferation of SN12C and A498." (PMID 24991762, 2014). "On the basis of the preclinical data we primarily hypothesized that baseline FDG-PET uptake would correlate with mTOR antitumor activity in renal cancer." (PMID 24156027, 2013). "A patient with renal cancer who had failed two multi-targeted antiangiogenesis inhibitors and an mTOR inhibitor had a >80 % reduction in tumor burden after five cycles of carfilzomib and continued on therapy for 13 cycles until disease progression with a dural-based brain metastasis." (PMID 23975329, 2013). "Next we examined the effect of constitutively active mTOR on renal cancer cell migration." (PMID 22685542, 2012). "However, coexpression of constitutively active mTOR with miR-21 Sponge significantly reversed the inhibition in migration of both renal cancer cell lines in response to miR-21 Sponge." (PMID 22685542, 2012). "In summary, our study identifies that phosphorylation of PRAS40 may lead to the activation of mTOR signaling pathway in CNI-induced rapid progression of human renal cancer." (PMID 21886838, 2011). "Laboratory experiments have shown that antiproliferative effects of mTOR inhibitors in renal carcinoma cells may result from the inhibition of essential survival pathways, complex cell cycle effects, induction of apoptosis, and autophagy." (PMID 18797463, 2008). "Mechanisms by which inhibition of mTOR may control tumour growth in patients with renal cancer remain unclear." (PMID 18797463, 2008). "If a direct effect of rapalogues against renal cancer cells is unlikely, temsirolimus may induce antitumour effects by targeting other cells with activated mTOR signalling such as the cells participating to tumour angiogenesis." (PMID 18797463, 2008). "We found that classic renal cancer–related genes such as VHL, PBRM1, TTN, and SETD2 had higher mutation frequencies in the TCGA-KIRC cohort, with PBRM1 having a higher mutation rate in XPS1 compared to XPS2 (43% vs. 37%), while mTOR had a lower mutation rate in XPS1 compared to XPS2 (6% vs. 10%)." (PMID 39882192, 2025). "Finally, we explored the impact of PYCR1 and PYCR2 on cell growth and migration in renal cancer cells, revealing that PYCR1 and PYCR2 may exert their effects on renal cancer by activating the mTOR signaling pathway." (PMID 39125668, 2024). "The mTOR signaling pathway is a crucial signaling pathway of cell energy metabolism, promoting substance metabolism and taking part in apoptosis and autophagy, inducing T cell function and differentiation, which plays a significant role in a variety of diseases, such as renal cancer." (PMID 38675412, 2024). "Therefore, ZNF471 could suppress the malignant phenotype of renal cancer by inhibiting the activation of the PI3K/AKT/mTOR signalling pathway." (PMID 38169650, 2024). "Consequently, drugs targeting PI3K, AKT, and mTOR could offer novel insights and therapeutic approaches for renal cancer treatment." (PMID 39092291, 2024).
renal carcinoma (continued). "Additionally, given the role of the PI3K/Akt/mTOR pathway in renal carcinoma, our findings suggest that targeting this pathway, along with CHKB-AS1, could be a promising strategy." (PMID 38093375, 2023). "Furthermore, the mTOR activity in the kidney has been identified in many different cell types and has been related to ischemia-reperfusion injury, interstitial fibrosis, and renal carcinoma." (PMID 36330055, 2022). "Thus, the mitochondrial remodeling noted following TEMS treatment in the malignant renal cancer cell lines may thus promote increased energy usage to antagonize responsiveness to the mTOR inhibitor." (PMID 32492043, 2020). "Therefore, mTOR inhibitors may be coupled with the CXCR4–CXCL12–CXCR7 axis inhibitors in renal cancer patients to prevent and/or overcome the mTOR drug resistance." (PMID 24991762, 2014). "In addition, our study defines a novel pathway, in which the overexpression of PRAS40 may limit CNI/Ras-induced and mTOR-mediated rapid progression of human renal cancer." (PMID 21886838, 2011). "Thus, our study clearly suggests that mTOR is a critical signaling molecule in CNI-induced tumorigenic pathway(s) that may lead to VEGF overexpression in renal cancer." (PMID 21886838, 2011). "It would also be of value to explore the interaction of PIEZO1 with known renal cancer drivers, such as VHL, HIF-1α, or mTOR, and to assess its impact on angiogenesis, metabolic regulation, and immune cell infiltration." (PMID 40724850, 2025). "Essential genes involved in the regulation of metabolic reprogramming in renal cancer are VHL, PTEN, Akt, mTOR, TSC1/2 and Myc." (PMID 38884097, 2024). "The primary genes that control the process of metabolic reprogramming in renal cancer are Myc, VHL, PTEN, Akt, mTOR, and TSC1/2 48-52." (PMID 38169635, 2024). "The main aim of this review is to present renal cancer types, dysregulation of PI3K/AKT/mTOR signaling pathway members, crosstalk with VHL/HIF axis, and carbohydrates, lipids, and amino acid alterations." (PMID 37176098, 2023). "Except for TGF-β/Smad signaling, other pro-fibrotic pathways such as WNT, mTOR, and NOTCH signaling pathways also contribute to tumorigenesis in renal cancer." (PMID 36910160, 2023). "In renal carcinoma cell lines, HCQ enhanced the activity of mTOR inhibitors, such as everolimus, inhibiting mitochondrial oxygen consumption and promoting apoptosis through inhibition of S6 phosphorylation." (PMID 36871010, 2023). "In our study, we have highlighted the roles of CHKB-AS1 and MAP4 in modulating the PI3K/Akt/mTOR pathway and contributing to NVP-BEZ235 resistance in renal carcinoma." (PMID 38093375, 2023). "As a major member of dual PI3K/mTOR inhibitors, NVP-BEZ235 has undergone Phase I/II trials for the treatment of some malignancies including renal carcinoma." (PMID 35082669, 2021). "In total, these findings support the view that the distinct inhibition of PI3K/Akt/mTOR signaling by Rapamycin, PP242, and NVP-BEZ235 was partially responsible for their varying inhibitory effects in human renal cancer cells." (PMID 35082669, 2021). "The mTOR inhibitor rapamycin (RAPA), which is being used for the treatment of both renal cancer and transplant patients, has many limitations." (PMID 32635337, 2020). "Consistently, we found that the AKT/mTOR pathway is activated in both renal cancer cell lines, suggesting that the activation of the AKT/mTOR pathway is a common event in renal cancer." (PMID 23690956, 2013). "Here, we evaluated the effect of the dual PI3K/mTOR inhibitor NVP-BEZ235, in combination with the multikinase inhibitor sorafenib on renal cancer cell proliferation and survival in vitro as well as on tumor growth in vivo." (PMID 21791089, 2011). "Together, the phosphorylation of PRAS40 is critical for the activation of mTOR in CNI-induced VEGF overexpression and renal cancer progression." (PMID 21886838, 2011).
renal carcinoma (continued). "Here, we examined the role of mTOR pathway in mediating CNI- and Ras-induced overexpression of VEGF in human renal cancer cells (786-0 and Caki-1)." (PMID 21886838, 2011). "Conversely, in patients with renal cancer who experience progression after initial treatment with sunitinib, sorafenib—a VEGF pathway inhibitor—has demonstrated superiority over tisorolimus, an mTOR pathway inhibitor." (PMID 40909959, 2025). "Notably, there is significant crosstalk between the VHL–HIF–VEGFR–mTOR and PI3K/AKT/mTOR pathways, forming a complex signaling network that synergistically promotes renal cancer progression." (PMID 39092291, 2024). "In summary, these results suggested that ZNF471 could interact with BANP in renal cancer cells and inactivate PI3K/AKT/mTOR signalling, thus further suppressing the malignant phenotype of RCC cells." (PMID 38169650, 2024). "It was demonstrated that HSF1 activation by mTOR (mammalian target of rapamycin) leads to higher expression of cancer stem-like cell markers by activating DNAJB8, which, in turn, enhances the expression of Sox2 in renal carcinoma cells under stressful conditions." (PMID 39682216, 2024). "In conclusion, the discovery of the mechanisms through which fibrotic signaling promotes tumorigenesis and aggressiveness in RCC provides inspiration for the development of anti-fibrotic therapies, such as mTOR inhibitors or anti-TGF-β antibodies, as novel therapeutic strategies for renal cancer." (PMID 36910160, 2023). "Their ability to modulate the inactivated Hippo pathway in mesothelioma, as well as inhibit AKT/mTOR, ERK and JAK/STAT3 pathways in renal cancer cells in vitro supported Meta-Analyses based studies showing a beneficial effect of statins for both overall survival and cancer-specific survival." (PMID 36293328, 2022). "Functionally, LTB4R promotes the migration, invasion, proliferation, and apoptosis of renal cancer cells; mechanistically, LTB4R influences the progression of renal clear cell carcinoma by regulating the AKT/mTOR signaling pathway and, thus, the development of renal clear cell carcinoma." (PMID 36429034, 2022). "Moreover, sinomenine enhanced renal carcinoma cell apoptosis by promoting autophagy and suppressing the PI3K/AKT/mTOR pathway." (PMID 34760016, 2021). "We observed that the RAPA + Honokiol combination treatment markedly down-regulated the level of phospho-Akt, phospho-mTOR and phospho-S6 in renal cancer cells; however, there was no significant change in the total protein levels." (PMID 32635337, 2020). "Thus, we first tested a variety of doses of the mTOR inhibitor (100 nM to 10 μM of TEMS) in 769-P, 786-O, A-498 malignant renal cancer cells as well as the normal immortalized HK-2 cell line." (PMID 32492043, 2020). "To elucidate whether miR-21-activated TORC1 contributes to proliferation of renal cancer cells, we cotransfected ACHN and Caki-2 cells with miR-21 Sponge and a constitutively active mTOR expression vector." (PMID 22685542, 2012). "Interestingly, we have demonstrated that the CNI-induced VEGF overexpression and renal cancer cell proliferation is inhibited by RAPA treatment, suggesting the possible role of mTOR in CNI-induced tumorigenic pathways that involves Ras activation." (PMID 21886838, 2011). "That seems to be particularly important in renal cancer, due to the frequent overproduction of proangiogenic and proinflammatory cytokines, which disrupts the angiogenic balance through the stimulation of the RAS/RAF/MEK/ERK and PI3 Kinase/AKT/mTOR signaling pathways." (PMID 36499030, 2022). "Considering the differential intrinsic expression and potentially differential PD-1/PD-L1 interaction intensity within the two (clear and papillary) types of renal carcinoma, one could speculate the activation of different signaling pathways (PI3K/AKT, MAPK, mTOR)." (PMID 36552000, 2022).
renal carcinoma (continued). "Previous studies reported that mTOR pathway, GSK3 pathway, AKT pathway, EIF4 pathway, MET pathway, NFAT pathway, and FAS pathway acted as essential factors in the development of renal cancer and that CHREBP2 pathway, EDG1 pathway, and CTCF pathway were also cancer-related pathways." (PMID 33102202, 2020). "In addition, the entire CXCR4–CXCL12–CXCR7 axis could activate the mTOR pathway and stimulate cell migration in human A498 and SN12C renal cancer cells." (PMID 30574021, 2018). "mTOR inhibitors are used clinically to treat renal cancer but are not curative." (PMID 22848625, 2012). "In addition, the mTOR pathway and the VEGF signaling pathway involved in the pathogenesis of renal cancer were also enriched in our current study (data not shown)." (PMID 36188228, 2022).
autism (161 papers, 2011 to 2025). Persistent deficits in social interaction and communication and interaction as well as a markedly restricted repertoire of activity and interest as well as repetitive patterns of behavior. "Ganesan H., Balasubramanian V., Iyer M., Venugopal A., SubramaniamM.D., Cho S.G., Vellingiri B. mTOR signalling pathway –a root cause for idiopathic autism?" (PMID 41536790, 2025). "PIK3CA functions as a catalytic subunit of the mTOR pathway and has previously been found to be associated with developmental delay and DM, including one individual diagnosed with autism." (PMID 39887636, 2025). "The mTOR signaling pathway activity and vitamin Davailability control the expression of most autism predispositiongenes." (PMID 41536790, 2025). "In the same study, we also showed that similar patterns of fronto-striatal hyperconnectivity are detectable in subsets of idiopathic autism patients, where they are associated with a gene coexpression network involving mTOR-Tsc2." (PMID 38996019, 2024). "Studies indicate that approximately 8-10% of autism cases are due to abnormal mTOR signaling pathways 9, and up to 58% of autism susceptibility genes are directly or indirectly associated with mTOR signaling pathways." (PMID 39113803, 2024). "Altered regulation of the RAS/MAPK and PI3K/AKT/mTOR pathways are e.g. associated with autism and other neurodevelopmental disorders, and with the development of cancer and alterations in these pathways are also involved in the development of TGCT." (PMID 37088800, 2023). "Dysregulation in the mTOR pathway has been linked to the development of autism, contributing to aberrant synaptic protein synthesis and associated symptoms, including macrocephaly, seizures, and learning deficits." (PMID 38138941, 2023). "Collectively, VB6 deficiency induces autism-like behaviors in rats by regulating mTOR-mediated autophagy in the hippocampus." (PMID 37200987, 2023). "PI3K-AKT/mTOR signaling pathway is highly associated with autism and various neurodegenerative diseases." (PMID 36768153, 2023). "In conclusion, based on in vivo experiments, our current study authenticates that VB6 deficiency induces autism-like behaviors in rats by regulating mTOR-mediated autophagy, which provides a new mechanism of ASD." (PMID 37200987, 2023). "mTOR signaling is also known to be associated with autism and other neurological and psychiatric disorders, suggesting its role in the recent evolution of the human brain." (PMID 37789379, 2023). "The AKT/mTOR pathway is a biological substrate for autism, and mutations in the AKT/mTOR gene cascade lead to an increase in autism-like behaviors by regulating translation to dendritic spines." (PMID 36768153, 2023). "GABA activation or mTOR inhibition offset the role of VB6 deficiency in autism-like behaviors and hippocampal GABA expression." (PMID 37200987, 2023). "Further, many monogenic alterations that greatly increase risk for the development of autism adversely impact the integrity of genes whose protein products normally act as brakes for the mTOR pathway, thereby resulting in excessive mTOR activity." (PMID 35113852, 2022). "Up to 58% of autism predisposition genes are related to the mTOR signaling activity directly or indirectly." (PMID 35422816, 2022). "In the Simons Foundation Autism Research Initiative (SFARI) database, three genes (BRAF, GRIN2A, MTOR) are identified as strong autism risk genes." (PMID 35883654, 2022). "We have bioinformatically demonstrated that autism spectrum and autoimmune disorders do share predisposition gene signatures due to mTOR signaling pathway controlling expression." (PMID 35055151, 2022). "Downregulation of DRD2 has been shown to activate AKT-mTOR (mammalian target of rapamycin) signaling 41,42, and activation of mTOR signaling has been implicated in the deficient synaptic pruning in the autism-spectrum diseases." (PMID 34750364, 2021).